ZYG11A (zyg-11 family member A, cell cycle regulator)
Description:
Probably acts as a target recruitment subunit in an E3 ubiquitin ligase complex ZYGA-CUL2-elongin BC.
Synonyms: ZYG11
Tractability: PROTAC: ubiquitination databases record sites on it.
Gene: Protein-coding gene on chromosome 1 (52,842,511 to 52,894,998, forward strand). Ensembl gene ENSG00000203995.
Subcellular location (Human Protein Atlas): Nucleoplasm
Gene Ontology:
Cellular component: Cul2-RING ubiquitin ligase complex
Genetic constraint (gnomAD): Loss-of-function variants: 49 observed, 61.44 expected, observed/expected ratio (o/e) 0.8, 90% interval 0.63 to 1.01. The upper end of that interval is the gene's LOEUF score, 1.01, which puts it in group 4 of 6, group 1 being the genes least tolerant of losing a copy. Missense variants: 703 observed, 779.38 expected, observed/expected ratio (o/e) 0.9, 90% interval 0.85 to 0.96. Synonymous variants: 265 observed, 285.51 expected, observed/expected ratio (o/e) 0.93, 90% interval 0.84 to 1.03.
Homologues: Orthologues: macaque ZYG11A (96% identical), rabbit ZYG11A (80% identical), pig ZYG11A (79% identical), mouse Zyg11a (73% identical), rat Zyg11a (72% identical), guinea pig ZYG11A (65% identical), tropical clawed frog zyg11b (56% identical), zebrafish zyg11 (51% identical), chimpanzee ZYG11A (42% identical), zebrafish zyg11l (40% identical), Caenorhabditis elegans zyg-11 (25% identical). Paralogues in human: ZYG11B (60% identical), ZER1 (25% identical).
Diseases named in the same sentence as ZYG11A in open-access papers:
ZYG11A is named in the same sentence as 15 diseases in open-access papers, as found by Europe PMC text mining. Sharing a sentence is not in itself a finding about the gene and the disease. The quoted sentences say what the papers report.
non-small cell lung carcinoma (5 papers, 2016 to 2021). A group of at least three distinct histological types of lung cancer, including non-small cell squamous cell carcinoma, adenocarcinoma, and large cell carcinoma. "One recent study has demonstrated an oncogenic function of the overexpressed ZYG11A gene in non-small cell lung cancer (NSCLC), being correlated with poor prognosis, in accordance with our data." (PMID 30899432, 2019). "Recently, our group demonstrated that ZYG11A serves as an oncogene in non-small cell lung cancer via regulating CCNE1 expression." (PMID 27107416, 2016). "ZYG11A was recognized as a potential oncogene in non-small cell lung cancer." (PMID 34220714, 2021). "Early studies have identified ZYG11A as a potential oncogene in non-small cell lung cancer." (PMID 34220714, 2021).
lung carcinoma (3 papers, 2016 to 2019). "High ZYG11A expression (as determined by a cut-off score of 140) was detected in 47 (56.6%) of the 83 lung cancer tissues, compared with only 12 (13.5%) of 89 adjacent normal tissue samples." (PMID 26771237, 2016). "Similarly to our data, ZYG11A knockdown in lung cancer-derived cell lines induced cell cycle arrest and inhibited proliferation." (PMID 31320996, 2019).
dwarfism (2 papers, 2019 to 2021). "Recent genome-wide association studies conducted on LS patients identified ZYG11A as a highly represented gene in this genetic type of dwarfism." (PMID 31320996, 2019). "Recent genomic analyses of Laron syndrome (LS) patients, a type of dwarfism under the spectrum of the congenital IGF1 deficiencies, allowed us to identify ZYG11A as a new downstream target for IGF1 action." (PMID 34220714, 2021).
endometrial cancer (2 papers, 2019 to 2021). Primary or metastatic malignant neoplasm involving the endometrium (mucous membrane that lines the endometrial cavity). "In view of the epidemiological and clinical correlations between the insulin/IGF1 signaling pathway and endometrial cancer risk and to explore the potential regulation of ZYG11A by IGF1, we investigated the expression of this gene in endometrial cancer-derived cell lines." (PMID 31320996, 2019). "Our data suggest that the ZYG11A gene constitutes a novel target for IGF1 action in endometrial cancer cells." (PMID 31320996, 2019). "Next, we investigated the effect of ZYG11A expression on endometrial cancer cell proliferation." (PMID 31320996, 2019). "In summary, our study has identified the ZYG11A gene as a new downstream target for IGF1 action, with potential relevance in endometrial cancer biology." (PMID 31320996, 2019).
Epithelial Ovarian Cancer (2 papers, 2021 to 2022). "ZYG11A, a member of ZYG11 family, has been identified to be involved in the regulation of cell cycle and division, and its expression in ovarian cancer was correlated with tumor stage." (PMID 35372049, 2022).
lung adenocarcinoma (2 papers, 2016 to 2019). A carcinoma that arises from the lung and is characterized by the presence of malignant glandular epithelial cells. "Next, to investigate the expression pattern and clinicopathological implications of SFN, GORASP2 and ZYG11A, we performed IHC using 171 cases of lung adenocarcinoma." (PMID 30899432, 2019). "Multivariate analysis also indicated that lymphatic permeation, vascular invasion, pathological stage, and expression of GORASP2 or ZYG11A were independent prognostic factors indicative of poor survival in patients with lung adenocarcinoma." (PMID 30899432, 2019). "We next used KEGG pathway analysis (DAVID Bioinformatics Resources 6.7) on a list of genes co-expressed with ZYG11A that was obtained from cBioPortal using both RNA-seq and microarray results of Lung Adenocarcinoma (TCGA, Provisional)." (PMID 26771237, 2016). "Since DNA demethylation-triggered overexpression of SFN has essential functions during the course of lung adenocarcinoma progression, we expect that GORASP2 and ZYG11A might also have some functional association in this tumor." (PMID 30899432, 2019).
breast carcinoma (1 paper, 2019). "This possibility is supported by results showing higher ZYG11A mRNA levels in malignant breast cancer-derived MCF7 cells than in benign MCF10A cells." (PMID 31320996, 2019).
ovarian tumors (1 paper, 2021). "This pattern of expression is consistent with a candidate tumor suppressor role of ZYG11A, at least in the context of ovarian tumors." (PMID 34220714, 2021).
tumor (9 papers, 2014 to 2024). "In this study, we present evidence that ZYG11A is over-expressed in NSCLC and that over-expression of ZYG11A is associated with greater tumor size and more advanced TNM stage." (PMID 26771237, 2016). "The ZYG11A expression is negatively correlated with the epithelial ovarian cancer histological grade, which suggests its potential as a candidate tumor suppressor." (PMID 35846145, 2022). "Our analyses provide evidence of reduced expression of ZYG11A in high grade tumors, consistent with a putative tumor suppressor role." (PMID 34220714, 2021). "The association between low ZYG11A levels and high histological grade identifies the ZYG11A gene as a candidate tumor suppressor." (PMID 34220714, 2021). "Our analyses provide evidence of reduced ZYG11A expression in high grade tumors, consistent with a putative tumor suppressor role." (PMID 34220714, 2021). "Despite this, we identified 2 new genes, GORASP2 and ZYG11A, which show hypomethylation and overexpression in invasive adenocarcinoma, suggesting that they have important functions in tumor cells." (PMID 30899432, 2019). "The expression profile of ZYG11A was further validated by qRT-PCR in 63 paired fresh NSCLC patients' tissues (tumor and adjacent normal lung tissues)." (PMID 26771237, 2016). "When focused on 108 paired tissues (the tumor and paired normal lung tissue from a same patient), ZYG11A was over-expressed in tumors compared with paired normal tissues." (PMID 26771237, 2016). "After excluding 8/90 tissue pairs for missing data/dots (7 tumor tissues and 1 normal tissues), expression of ZYG11A protein was higher in tumor tissues compared with their relative normal tissues (in 67/82 tissues examined)." (PMID 26771237, 2016). "Moreover, over-expression of ZYG11A was positively correlated with bigger primary tumor size (p=0.016) and more advanced TNM stage (p=0.014)." (PMID 26771237, 2016). "Moreover, we identified four putative tumor-specific cryptic peptides from ZYG11A, RPL36A-HNRNPH2, CLIC1 and RPL31 that were decreasingly presented upon MAPKi in SK-Mel-28 wt but were unaffected in SK-Mel-28 dr cells, indicating a direct link to MAPK signaling." (PMID 39835134, 2024). "Despite DNA demethylation at the promoter region might be rare relative to DNA hypermethylation, we identified 2 new genes, GORASP2 and ZYG11A, which show hypomethylation and overexpression in invasive adenocarcinoma, suggesting that they have important functions in tumor cells." (PMID 30899432, 2019). "The tumor suppressive partners comprise three highly significant binding components: MIR99AHGlncRNA/PIK3R3, miR-661/ZYG11A, and PPP2R2B/ZNF136 (Supplementary Excel Files S4 and S5)." (PMID 36289596, 2022). "Our study suggests that ZYG11A is hyper-expressed in NSCLC and correlates with larger primary tumor size and more advanced TNM stage." (PMID 26771237, 2016). "ZYG11A can promote proliferation, migration, and invasion of NSCLC cells in vitro and accelerate tumor growth in vivo." (PMID 26771237, 2016). "Compared with controls, the sh-ZYG11A group showed less PCNA staining, suggesting that ZYG11A knockdown could inhibit tumor growth in vivo." (PMID 26771237, 2016). "Then Human Protein Atlas immunohistochemistry (IHC) analyses showed that ZYG11A was not expressed in normal lung tissues, but was expressed in 4 out of 12 (33.3%) NSCLC tumor tissues." (PMID 26771237, 2016).
cancer (4 papers, 2016 to 2021). A tumor composed of atypical neoplastic, often pleomorphic cells that invade other tissues. "Future studies must address the paradoxical high expression of ZYG11A in LS, a condition associated with cancer protection." (PMID 31320996, 2019). "By analyzing the TCGA_LUNG_exp_HiSeqV2-2015-02-24 dataset, compared with normal tissues, ZYG11A expression was 5.88-fold hyper-expressed in cancer tissues (p<0.0001)." (PMID 26771237, 2016). "Xenograft assays showed that depletion of ZYG11A suppressed proliferation of cancer cells in vivo, while flow cytometric analysis indicated that si-ZYG11A treatment strongly inhibits G1 cell cycle progression, without increased apoptosis." (PMID 26771237, 2016). "Transwell and Matrigel assays further revealed that ZYG11A knockdown undermines cancer cell migration and invasion abilities." (PMID 26771237, 2016). "Given our findings that ZYG11A knockdown decreased cancer cell proliferation, migration, and invasion and promoted G1 cell cycle arrest, we sought to determine expression of cell cycle-related genes in ZYG11A knockdown cells using qRT-PCR and western blot analyses." (PMID 26771237, 2016). "However, among the as yet unknown genes, ZYG11A showed a much higher fold-change between cancer and paired normal tissues (with an average 5.88 fold-change in the TCGA-LUNG dataset, p<0.00001)." (PMID 26771237, 2016). "The clinical implications of ZYG11A expression in EOC (and, probably, other types of cancer) merit further investigation." (PMID 34220714, 2021).
ZYG11A also shares sentences with these, for which no sentence is quoted: ovarian cancer (2 papers); diabetes (1); Laron syndrome (1); lymph node metastasis (1); Obesity (1).